CD4 (CD4 molecule)
Diseases named in the same sentence as CD4 in open-access papers (continued):
Sharing a sentence is not in itself a finding about the gene and the disease.
COVID-19 (continued). "Furthermore, studies of patients with COVID-19 show that the presence of SARS-CoV-2–specific CD4+ and CD8+ T cells is associated with lower disease severity." (PMID 34591596, 2021). "This has been attributed to chronic inflammation mediated by adipose tissue and CD4+ lymphopenia with a biased phenotype towards Th17 and Th22 responses, which might explain the higher susceptibility for COVID-19 adverse outcomes." (PMID 34566957, 2021). "However, while the HIV microvasculopathy has well-known associations with low CD4 counts and laboratory evidence of immune deficiency, we cannot, at this stage, comment upon the association of COVID-19 retinopathy with laboratory profile." (PMID 34249972, 2021). "Indeed a recent report did show that COVID-19 convalescent individuals infected in the early phase of the pandemic mounted a robust CD4+ and CD8+ T cell responses against these new variants." (PMID 34965282, 2021). "In COVID-19, there is a striking loss of T cells, particularly of naïve CD4+ T cells, but many effector and memory subsets are proportionally increased (although due to lymphopenia this may still represent a reduction in absolute numbers)." (PMID 33575657, 2021). "In COVID-19, the loss of cytokine production (IL-2, IFNγ or TNFα) and antiviral activity (CD107a and Granzyme B) in both CD4+ and CD8+ T cells may be an important contributing factor to disease severity." (PMID 33575657, 2021). "Similarly, Mathew and colleagues examined blood from 125 hospitalized COVID-19 patients and found that more severe COVID-19 was associated with lower frequencies of both CD4+ and CD8+ T cells." (PMID 33815415, 2021). "As expected, diminished frequencies and absolute counts of leukocytes, naïve, activated, and effector (Th1 or Th17) CD4+ T cells can be associated with a remnant of lymphopenia already observed in the majority of COVID-19 individuals and recovered individuals." (PMID 35069575, 2021). "Moreover, severe COVID-19 is associated with dysregulation of T-cells, causing lymphopenia and exhaustion of CD4+ and CD8+ T cells." (PMID 34975885, 2021). "Previous reports have shown that SARS-CoV-2 peptide stimulation significantly induces IFNγ production by CD4+ T cells from unexposed individuals and that the Th1 response is associated with an effective resolution of infection and symptoms in COVID-19." (PMID 35822004, 2021). "Moreover, it has been observed that the most severe cases of COVID-19 are associated with a reduction in CD4+ T, T-lymphocytes, CD8+ T cells and an increase in levels of C-reactive protein, D-dimer, ferritin, IL-6, IL-2R40." (PMID 34824310, 2021). "Similarly, Cox proportional hazards analysis was performed in patients with severe COVID-19, and the results also suggested that decreased CD4+T cell level was an independent risk factor for in-hospital death." (PMID 33435865, 2021). "In SARS-CoV-2-infected individuals, lymphopenia with drastically reduced CD4+ and CD8+ T cells correlates with Coronavirus disease 2019 (COVID-19)-associated disease severity and mortality." (PMID 34194438, 2021). "COVID-19 may cause the reduced T lymphocytes, especially CD4 + T and CD8 + T cells, leading to reduced IFN-γ production, which may be related to the severity of disease." (PMID 32762665, 2020). "However, the severe COVID-19 cases showed an increase in IL-6, IL-2R, IL-10, and TNFα secretion associated with a severe decrease in T cells, particularly CD4+ T cells." (PMID 32793246, 2020). "CD4+ T cells may also contribute to the production of cytokines in the cytokine storm, which is a main mechanism associated with the pathogenesis of COVID-19 in old individuals." (PMID 33193377, 2020). "Another important finding of this study are the description of parameters associated with a fatal outcome to COVID-19, including a high neutrophil/lymphocyte ratio, expression of PD-1 on CD4+ and CD8+ lymphocytes, and the expression of HLA-DR on CD4+ T cells in patients with a marked lymphopenia." (PMID 33324414, 2020).
COVID-19 (continued). "Recent evidences indicates that COVID-19 is associated with CD4+ and CD8+ T-cell lymphopenia." (PMID 33375371, 2020). "In addition, the L in the group A and tuberculosis group has no significantly different, but tuberculosis mainly causes the reduction of CD4+T cells, while the COVID-19 is CD8+T cells." (PMID 33046047, 2020). "Decreases in CD4+ T-cell levels, and lymphopenia and abnormal cytokine levels were common features in cases of COVID-19, which might be a critical factor associated with disease severity and mortality." (PMID 33015108, 2020). "The additional report suggested that COVID-19 illness might be implicated with CD4+ and CD8+ T cells depletion through acting on lymphocytes, especially T lymphocytes." (PMID 32822430, 2020). "This alteration in inflammatory response observed in COVID-19 patients could be associated with a reduction in CD4+, CD8+, and NK lymphocytes." (PMID 32490931, 2020). "Severe COVID-19 correlates with preferential CD8+ lymphopaenia as compared to loss of CD4+ T-cells." (PMID 33362759, 2020). "Second, the immune dysregulation associated with COVID-19, with reduced numbers of T lymphocytes, CD4+T, and CD8+T cells, may alter innate immunity." (PMID 33145132, 2020). "The authors next asked the question of whether stronger SARS-CoV-2-specific CD4+ T cell responses were associated with higher antibody titers in COVID-19 cases." (PMID 32616709, 2020). "Additionally, we determined that neutrophilia, lymphocytopenia, low number of CD4+ T cells, and decreased level of C3 were the immunity-related risk factors that can predict mortality of patients with COVID-19." (PMID 32746940, 2020). "Another finding in COVID-19 that is associated with an adverse outcome is the rapid development of lymphopenia, whereby CD4+ T-cells are more severely reduced than CD8+ T-cells, the reason being unknown." (PMID 32806708, 2020). "However, all the results obtained in the different subanalyses performed are consistent, showing an association between CD4+ T cells and disease severity in the early stages of COVID-19." (PMID 33182268, 2020). "When SARS-CoV-2 vaccines were rolled out, PLWH—especially those with current CD4 + T-cell count < 200/μL, evidence of an opportunistic infection, and/or with a detectable viral load—were prioritized for vaccination, due to the potential higher risk for worse COVID-19 outcomes." (PMID 36680700, 2023). "In COVID-19 patients, immune profiling has unveiled dynamic alterations in both innate and adaptive immune cells, with specific natural killer-cell receptors and IgM+ B cells linked to significant CD4 and CD8 T-cell exhaustion, thereby elevating the risk of intubation and mortality." (PMID 37763674, 2023). "Moreover, especially the CD4+/CD8+ ratio may be used as an important marker for assessing the individual risk of severe COVID-19 in PLWH and to determine a suitable vaccination strategy for individuals with inadequate responses to antiviral therapy." (PMID 36839516, 2023). "Notably, severe COVID-19, albeit having an increase in activated effector cell populations as seen with other disease severities, is associated with lymphopenia and profound functional impairment of CD4 and CD8 T cells." (PMID 36670287, 2023). "HIV is a disease of a chronic inflammatory state, and elevated interleukin (IL)-6 levels are associated with older age and higher BMI hence higher viral replication and low nadir CD4+ T cell count could be associated with the poor outcome when infected with COVID-19." (PMID 37288215, 2023). "To identify immunological parameters differentially expressed in circulating immune cells of COVID-19 patients with MD or SD, we evaluated the expression of activation/exhaustion surface markers, intracellular cytokines, and cytotoxicity-associated molecules in B lymphocytes, CD4+ and CD8+ T cells." (PMID 37809093, 2023). "Also, the severity of COVID-19 was linked to a type of CD4+ and CD8+ T cells that were very active." (PMID 36679947, 2023).
COVID-19 (continued). "In addition, CD4 count and lymphopenia, are known to be associated with disease severity and could have an impact on the evolution of COVID-19, as one of the main mechanisms underlying COVID-19-related morbidity and mortality is cytokine storm." (PMID 35031068, 2022). "Moreover, PLWH, especially those with undiagnosed or uncontrolled infections, low CD4 count, opportunistic infections and a high viral load, may present with severe COVID-19 and are at higher risk of death." (PMID 35202217, 2022). "Furthermore, long-term lymphopenia, hyperinflammation, lung tissue injury and imbalance in CD4+ T cell subsets associated with COVID-19 could propagate M. tuberculosis infection and disease progression." (PMID 35216349, 2022). "Moreover, high levels of tissue-resident memory-like CD4+ T cells expressing high amounts of the genes encoding the proinflammatory cytokines IL-17A/F and GM-CSF were identified in the lungs of patients with COVID-19 even after clearance of the virus." (PMID 36146622, 2022). "However, and taken together, our results suggest that the pathogenic role of CD4 T lymphocytes could be evoked during severe COVID-19 because steroids classically damper the T-cell responses and are associated with a better outcome." (PMID 35529881, 2022). "Moreover, a severity-associated decrease in CD4+ T lymphocytes was observed in males with COVID-19." (PMID 35248063, 2022). "The frequencies of PD-1+ICOS+cTfh, cytotoxic CD4+T and exhausted T cells were strongly expanded in COVID-19 patients, particularly in severe patients compared to healthy individuals, which suggested that extensive T cell dysfunction was associated with COVID-19 severity." (PMID 34603308, 2021). "Age ≥ 65 years, CK ≥ 180 U/L, and CD4+ T-cell counts <300 cells/μL at admission were risk factors independently associated with disease progression to severe COVID-19 during 14 days after admission and are therefore potential markers for disease progression in patients with milder COVID-19." (PMID 33336038, 2020). "Furthermore, low CD4+ T cell counts was a risk factor of death in patients with confirmed COVID-19." (PMID 32746940, 2020). "Patients with severe COVID-19 also show lymphocytopenia, which mostly affects the CD4+ T-cell subset and correlates with stronger cytokine storm." (PMID 41490093, 2026). "CD4+/CD8+ ratio has been used as a quantitative prognostic risk factor in viral infections and some studies demonstrated its role in COVID-19 prediction of disease severity." (PMID 40718799, 2025). "Compared to other respiratory infections, an exclusive pathological immune signature with signals of T-cell exhaustion, particularly in CD4 T-cell populations, has been suggested in adult patients with severe COVID-19." (PMID 41011738, 2025). "This study assessed the antibody response in PLWH with CD4 T-cell levels ≤200 cells/mm3 compared to those with higher levels, following a bivalent mRNA COVID-19 vaccine booster." (PMID 40299994, 2025). "In conclusion, PWH with a CD4+ T-cell count < 200 cells per μL had lower humoral responses over the two years following a primary COVID-19 vaccination series." (PMID 40388467, 2025). "Paired analysis of CD25 levels in COVID-19 patients revealed unaltered CD25 expression on CD4+ T cells and only a slight reduction of CD25 on CD8+ T cells at 6 M follow-up compared to acute disease." (PMID 41310351, 2025). "Despite COVID-19 individuals having a discreet increase in the frequency of CD4+T-bet+ T cells following spike stimulation, compared to HD, the GATA3/T-bet ratio was not modified." (PMID 40458413, 2025). "(C) Patient related: advanced age (>65 years old), and specific COVID-19 immunological alterations, including a high level of pro-inflammatory cytokines and low levels of CD4/CD8 lymphocytes T." (PMID 40430786, 2025). "Host defense mechanisms induced by COVID-19 vaccination involve four key components: neutralizing antibodies, memory B cells, CD4+ T cells, and CD8+ T cells." (PMID 40733728, 2025).
COVID-19 (continued). "COVID-19 has a total of eight cell types, CD4 (CD4 T-cell), CD8 (CD8 T-cell), B (B-cell), Mono (Monocyte), NK (Natural killer), DC (Dendritic cell), Plasma (Plasma-cell), and Mega (Megakaryocyte)." (PMID 41139925, 2025). "Increased activation markers in CD4+ T-cells and decreased indoleamine 2,3-dioxygenase expression in DCs were observed in COVID-19 participants." (PMID 40330474, 2025). "It has been reported that acute COVID-19 rapidly induced SARS-CoV-2-specific T cell responses (CD4+ and CD8+) to limit viral replication in the upper respiratory tract; these responses are independent of neutralizing antibodies." (PMID 40266218, 2025). "Of note, IR also showed a similar spike-specific CD4+ T cell repertoire and number of spike-specific CD4+ T cell responses after COVID-19 mRNA vaccination compared with HC." (PMID 41212052, 2025). "It was reported that 100% of CD4+ T cells were re-stimulated with S pools in an analysis with PBMCs from convalescent patients with COVID-19." (PMID 40487437, 2025). "CD4+ T cells were detected in significantly higher numbers in response to COVID-19 antigens (S, S1, and NMO) 4 weeks after the first booster than after the second booster." (PMID 41251472, 2025). "This study revealed distinct immune cell signatures, notably implicating neutrophils, monocytes, and CD4+ T cells in COVID-19 pathophysiology." (PMID 40733671, 2025). "Controls-LS exhibited significant differences compared to COVID-19+ cases in various immune cell subsets, including T and B lymphocytes, CD4 and CD8 maturation markers, and markers of cellular senescence and inflammation." (PMID 41573558, 2025). "The differences in T cell ratios between disease groups were attributable especially to a relative increase in regulatory, Tem1 and central memory CD4+ T cells in Non-COVID-19 and Post-Vaccination." (PMID 39994453, 2025). "Recent studies have showed that Tα1 therapy can benefit elderly COVID-19 patients by modulating T lymphocyte responses, specifically by increasing CD4+ and CD8+ T cell populations while preventing excessive activation of CD8+ T cells." (PMID 40969554, 2025). "The productive COVID-19 CD4 repertoires showed proportionally increased usage of only one combination (TRBV20-1 × TRBVJ1-5), which was not identified in the non-productive analysis." (PMID 40331338, 2025). "In COVID-19, the immune response of lymphocytes is mediated mainly by CD4+ T cells, which differentiate into type 1 T helper (Th1) cells and are responsible for producing antiviral cytokines such as interferon-gamma (IFN-γ)." (PMID 39859379, 2025). "Other studies suggest that a low CD4+ T cell count (<200 μL/L) predicts radiographic progression in severely and critically ill COVID-19 patients." (PMID 40718799, 2025). "The detailed analysis indeed revealed that the number of CD4+ effector memory T cells are higher in patients with mild COVID-19, whereas the number of MAIT/NKT increased with COVID-19 severity." (PMID 40557167, 2025). "For instance, CD4 counts <200 were shown to have a three-fold increase in the hazard of severe COVID-19 outcomes among PLHIV." (PMID 41283262, 2025). "Our results are consistent with a study that showed that SARS-CoV-2-infected human CD4+ T helper cells, but not CD8+ T cells, are present in blood and bronchoalveolar lavage CD4+ T helper cells of severe COVID-19 patients." (PMID 40429912, 2025). "The present study demonstrated that a heterologous second booster dose of BNT162b2, administered following a primary two-dose CoronaVac regimen for COVID-19 vaccination, rapidly induced CD4+ T and B cell responses that were maintained for at least 6 months." (PMID 41251472, 2025). "In our study, we also observed a higher proportion of neutrophils in COVID-19, while the proportion of B lymphocytes, CD4 and CD8 T lymphocytes was relatively low." (PMID 40495223, 2025).
COVID-19 (continued). "Among the participants in the COVID-19 group, significantly higher CD4+ T cell responses to S, S1, and NMO antigens were observed at 24 weeks than at 4 weeks after the second booster." (PMID 41251472, 2025). "At 4 and 24 weeks after the second booster, CD4+ T cells continued to respond to the COVID-19 antigens (S, S1, and NMO), whereas CD8+ T cell responses were no longer detectable." (PMID 41251472, 2025). "COVID-19 vaccination has been reported to be just as effective in PLWH on ART with normal CD4+ T cell counts and a suppressed viral load, compared to uninfected controls, in countries outside of the US and in small US samples." (PMID 40432125, 2025). "Our study also showed that PLWH with CD4+ T cell counts <500 cells/μL developed a weaker and less durable immune response after two doses of an inactivated COVID-19 vaccine." (PMID 40838719, 2025). "HIV serostatus, viral load, CD4+ T cell count, and COVID-19 vaccinations were abstracted from medical records." (PMID 40432125, 2025). "Our two-year follow-up shows that PWH with a CD4+ T-cell count < 200 cells per μL had consistently lower antibody levels after a primary COVID-19 vaccination series compared to PWH with a CD4+ T-cell count ≥ 200 cells per μL." (PMID 40388467, 2025). "We applied DiSC to analyze 11 subtypes of PBMCs from the COVID-19 study introduced above and conducted Gene Ontology (GO) enrichment analysis on the DE genes in CD4+ and CD8+ T cells." (PMID 40444783, 2025). "CD4+ T cells in patients who recovered from mild COVID-19 were found to gain a typical memory phenotype with high expression of IL-7Rα." (PMID 40378227, 2025). "Shima studied lymphocyte subsets in pediatric patients and found that the CD4+/CD8+T cell ratio was lower in patients with severe COVID-19 than in those with mild/moderate forms of the disease." (PMID 41169892, 2025). "Although myeloid responses were similar across all groups, the Post-Vaccination group showed a higher proportion of CD4+ T cells, and the Post-COVID-19 group exhibited an expansion of cytotoxic CD8+ T and natural killer cells." (PMID 39994453, 2025). "Conversely, in severe SARS-CoV-2 infection (COVID-19), intense viral replication triggers widespread CD4+ T cell activation and differentiation." (PMID 40806563, 2025). "In contrast, the non-COVID-19 group exhibited significantly higher CD4+ T cell responses 4 weeks after the second booster." (PMID 41251472, 2025). "There are 14 types of immune cells with differential infiltration between COVID-19 and control samples, such as activated CD4 T cell, memory effector CD4 T cell and follicular helper T cell." (PMID 40300201, 2025). "In this context, high frequencies of spike protein-specific CD4+T cell responses have been reported in blood samples of COVID-19 convalescent." (PMID 40698364, 2025). "Meanwhile, CD4-mediated SARS-CoV-2 infection of T helper cells can contribute to a weakened immune response in patients with COVID-19." (PMID 41155463, 2025). "On the other hand, patients with COVID-19 present, at a peripheral level, low counts of CD4+ and CD8+ T cells, but with a higher proportion of pro-inflammatory CD4+ Th17 T cells, along with high levels of pro-inflammatory cytokines." (PMID 40406515, 2025). "Although PWH sometimes exhibits weaker vaccine responses, particularly at lower CD4+ counts, our findings indicate that mRNA-based COVID-19 vaccination remains broadly effective." (PMID 40432092, 2025). "A more accelerated response of specific CD4+ T cells has been related to mild cases of COVID-19, while the absence or prolonged reduction of these cells has been identified in severe or fatal cases." (PMID 39859379, 2025). "CD4+ T cells negatively correlated with convalescence period, except in a vaccinated COVID-19+ female (sample #15)." (PMID 40698364, 2025). "All patients with COVID-19 exhibited a significantly higher expression of TIM-3 on both CD4+ and CD8+ T cells compared to controls." (PMID 40005306, 2025).